UQCRC2 (ubiquinol-cytochrome c reductase core protein 2)
Diseases named in the same sentence as UQCRC2 in open-access papers (continued):
Sharing a sentence is not in itself a finding about the gene and the disease.
tumor (18 papers, 2010 to 2025). "Since we detected a 10-fold increase in CSF-1R-dependent phosphorylation of UQCRC2, this raises that possibility that this modification may downregulate it's activity, thus causing a similar loss of activity as observed in tumor cells with lower levels of UQCRC2 expression." (PMID 21049007, 2010). "Immunohistochemistry showed that the levels of SDHB and UQCRC2 in tumor region (T) were higher than those in para-carcinoma (P) region in patients." (PMID 39856069, 2025). "OXPHOS-related proteins (e.g., ATP5F1B, NDUFA9, UQCRC2) were broadly downregulated in tumor tissues, spanning multiple core subunits of the five complexes of the mitochondrial electron transport chain, suggesting impaired mitochondrial energy production." (PMID 41480141, 2025). "At the metabolic level, key proteins in the oxidative phosphorylation pathway-such as ATP5F1B, NDUFA9, and UQCRC2—were consistently downregulated across all tumor samples, covering multiple core subunits of the mitochondrial respiratory chain complexes." (PMID 41480141, 2025). "In this study, we report that the antitumor peptide JP1 regulated mitochondrial metabolic reprogramming through AMPK/FOXO3a/UQCRC2 signaling, which improved the tumor microenvironment hypoxia." (PMID 37192004, 2023). "As expected, we confirmed that JP1 regulates mitochondrial metabolic reprogramming of B16F10 and LLC cells through JP1-mediated AMPK/FOXO3a/UQCRC2 signaling, thereby improving the hypoxic state of the tumor microenvironment." (PMID 37192004, 2023). "JWA promotes mitochondrial metabolic reprogramming by regulating AMPK/FOXO3a/UQCRC2 signaling to improve the tumor microenvironment hypoxia, thereby inhibiting tumor metastasis." (PMID 37192004, 2023). "In this study, we confirmed that JP1 regulates the mitochondrial metabolic reprogramming of B16F10 and LLC cells through JP1-mediated AMPK/FOXO3a/UQCRC2 signaling, which improves the tumor microenvironment hypoxia." (PMID 37192004, 2023). "Specifically, JP1 regulated the mitochondrial metabolic reprogramming through AMPK/FOXO3a/UQCRC2 signaling, which improves the tumor microenvironment hypoxia." (PMID 37192004, 2023). "Tumors with up-regulated UQCRC2 expression exhibited decreased tumor proliferation, as evidenced by Ki67 and hematoxylin and eosin staining." (PMID 32742452, 2020). "Moreover, some credible results suggest that UQCRC2 is involved in many tumors as either an oncogene or a tumor suppressor gene." (PMID 32742452, 2020). "In addition, protein expression of ATP5A and III (ubiquinol-cytochrome c reductase 2 [UQCRC2]) and also the expression of CS were significantly increased, while the expression of Ldha was reduced in the tumour biopsies from the LW group." (PMID 31664147, 2019). "However, the correlation between UQCRQ, NDUFB7 and UQCRC2 in modulating mitochondrial energy generation and tumour progression remains unclear and needs to be confirmed by further experiments." (PMID 32757436, 2020). "Therefore, the miR-370/UQCRC2 axis may regulate EMT signaling pathways to affect tumor proliferation and metastasis and is, thus, a potential target for GC treatment." (PMID 32742452, 2020). "Other proteins of our founded subnetwork, including COX4I1, UQCRC2, ATP5J (ATP5PF), and ENSP00000400168 (ATP5MF-PTCD1), and UQCRQ also play a role in mitochondrial ATP synthesis; they are also involved in tumor initiation, growth, and metastasis." (PMID 38637790, 2024). "In the present study, the levels of SDHA, UQCRC2, MT-CO1 and ATP5F1A were significantly reduced in the tumor periphery compared to the control tissue." (PMID 31167495, 2019). "Similarly, the levels of SDHB and UQCRC2, as examined by immunohistochemistry, were also increased in HCT15-AA tumor grafts compared with HCT15 tumor." (PMID 39856069, 2025).
tumor (continued). "Except for the protein content of β-F1-ATPase of OXPHOS, the amount of ubiquinol-cytochrome c reductase core protein 2 (COREII) of complex III of the respiratory chain, HSP60 and of ATPase inhibitory factor 1 (IF1) increased significantly in tumor when compared to NAT." (PMID 35534478, 2022). "The protein expression of UQCRC2 was markedly downregulated in tumor tissues compared to its expression in non-carcinoma tissues." (PMID 32742452, 2020). "However, UQCRC2 expression did not correlate with other clinicopathological features in GC patients, including sex, age, and tumor diameter." (PMID 32742452, 2020). "UQCRC2 expression was reduced by SIRT6 silencing in MDA-MB-231, but not in Sirt6+/− mouse tumor masses." (PMID 33482921, 2021).
cancer (13 papers, 2010 to 2025). A tumor composed of atypical neoplastic, often pleomorphic cells that invade other tissues. "The expression of UQCRC2 has been shown to be associated with the anti-cancer effect of HSP60-regulated mitochondrial oxidative phosphorylation." (PMID 30813616, 2019). "Moreover, altered expression of proteins (NDUFS1, SOD1, SERPINA5, and UQCRC2) involved in sperm fertility potential and motility suggests that the fertility of cancer patients may be at risk due to the aberrant expression of critical sperm proteins." (PMID 32942548, 2020). "Recent evidence points toward a close relationship between UQCRC2 and human diseases, particularly cancers." (PMID 34565283, 2021). "As the key subunits of the ETC complex III, the ubiquitin–cytochrome c–reductase complex core proteins 1 and 2 (UQCRC1 and UQCRC2) have been reported to be either upregulated or downregulated in various cancers." (PMID 34361072, 2021). "In the present study, UQCRC2 was underexpressed in cancer patients, indicating multiple protein dysregulations in the mitochondria of spermatozoa regardless of the type of cancer, as demonstrated by Western blot analysis." (PMID 32942548, 2020). "Western blot validation of NDUFS1 and UQCRC2 protein expression in cancer patients were in accordance with the proteomic results." (PMID 32942548, 2020). "The analysis revealed the underexpression of NDUFS1 and UQCRC2 in all the cancer types compared to the fertile men." (PMID 32942548, 2020). "UQCRC2 was lost in 2% of the tumors and in 1% of the benign prostate tissue, whereas MT-CO1 loss was observed only in carcinomas (4%)." (PMID 30538797, 2018). "UQCRC2 expression levels were lower in GC tissues than non-carcinoma tissues." (PMID 32742452, 2020). "The oncogenic role of UQCRC2 is indicated by its overexpression in CRC and human lung adenocarcinomas, as well as its correlation with cancer invasion and metastasis." (PMID 34361072, 2021). "Particularly, an increase of proteins involved in redox balance, antioxidant defenses (CS, NDUFAF7, UQCRC2) and mitochondrial morphology (IMMT) was observed while cancer promotion proteins (DIABLO, TCPT) decreased." (PMID 33801925, 2021). "Furthermore, an analysis of the relationship between infiltration estimation and gene expression in gene modules revealed that T-cell CD4+ Th1 in genes ERRFI1, ZBED5, UQCRC2, ZNF146, ABHD17A, YWHAZ, and especially PLSCR4 showed a negative correlation in nearly 40 types of cancer." (PMID 38464509, 2024).
UQCRC2 also shares sentences with these, for which no sentence is quoted: Parkinson disease (4 papers); Huntington disease (3); colon cancer (2); infection (2); liver dysfunction (2); Mitochondrial complex III deficiency, nuclear type 5 (2); Mitochondrial encephalopathy (2); Sepsis (2); Ataxia (1); autism (1); bladder cancer (1); cardiomyopathy (1); cardiovascular disease (1); childhood cancer (1); cleft lip (1); colon adenocarcinoma (1); coronary artery disease (1); diabetes (1); Down syndrome (1); gastric adenocarcinoma (1); Hodgkin’s disease (1); hyperthyroidism (1); Infertility (1); Insulin resistance (1); keloid (1); leukemia (1); lung adenocarcinoma (1); lymphoma (1); male infertility (1); metabolic acidosis (1).
A further 16 diseases each share a sentence with UQCRC2 in 1 paper.